GIPR (gastric inhibitory polypeptide receptor)
Diseases named in the same sentence as GIPR in open-access papers (continued):
Sharing a sentence is not in itself a finding about the gene and the disease.
Obesity (continued). "An alternative explanation could be that GIPR targeting produces a relatively weak anorectic signal and thus appetite reduction is only possible in models where appetite regulation is disrupted, for example, HFD‐induced obesity." (PMID 41287212, 2026). "Importantly, both strategies have been translated into efficacious obesity pharmacotherapies when combined with GLP‐1R agonism; tirzepatide, a marketed GIPR/GLP‐1R dual agonist and maridebart cafraglutide, a GIPR antagonist/GLP‐1R agonist currently in phase III clinical trials." (PMID 41287212, 2026). "Unimolecular GLP1R/GIPR dual agonists not only amplify the metabolic benefits of GLP-1 therapies but may also reduce common side effects, offering an effective strategy for managing obesity and T2D-related conditions." (PMID 40166681, 2025). "Regardless, dual agonists targeting both GLP1R and GIPR decrease body weight and improve glucose tolerance in animal models of obesity and T2D in mice, non-human primates and obese patients with and without T2D [5,] with greater efficacy than GLP1R agonism alone." (PMID 38653401, 2024). "Currently, there are other dual GIPR/GLP-1R agonists available, such as GLP-1R/GR (glucagon receptor), GLP-1R/AR (amylin receptor), and GLP-1R/NPYR (peptide YY binds to neuropeptide Y receptors) and even triple agonists that can activate GIPR to treat obesity and T2DM." (PMID 38987789, 2024). "The glutamatergic neuron GIPR KO (GIPRΔGLUT) was not protective against HFD-induced obesity." (PMID 39612941, 2024). "Moreover, GIPR has not been the same focus of industry/academic efforts to produce antibodies, since GIPR agonism/antagonism has only just emerged as a viable option for diabetes/obesity therapy." (PMID 34911028, 2021). "Although our transcriptomic search did not retrieve studies focusing on these pathways, many anti-obesity drugs target GPCRs and peptide hormones (e.g., GLP-1R/GIPR dual agonists)." (PMID 41303351, 2025). "While early studies demonstrated the clinical potential of GIPRA in rodent models of type 2 diabetes/obesity, development of GIP agonists for human use was largely curtailed by GIPR downregulation, the lack of glycemic benefit of GIPRA, as well as the concept that GIPR agonism drives obesity." (PMID 38360354, 2024). "However, the apparent lack of GIP efficacy in patient with T2D coupled with the obesity protective phenotype of GIPR knockout mice, initially discouraged the development of GIPR agonists for diabetes therapy and even suggested that development of GIPR antagonists might be expedient." (PMID 35846282, 2022).
type 2 diabetes (80 papers, 2010 to 2026). "A high-fat diet attenuates type 2 diabetes risk via interaction with GIPR, whereas a high-carbohydrate diet elevates this risk through the same genetic interaction." (PMID 41190158, 2025). "Their receptors, GLP-1R and GIPR, are primarily localized to pancreatic islet cells and implicated in the treatment of type 2 diabetes mellitus (T2DM)." (PMID 31998717, 2019). "Human studies of GIPR common gene variants found a significant interaction between the rs10423928 SNP and a high-fat/low carbohydrate diet on risk of type 2 diabetes." (PMID 25825681, 2015). "Additionally, SNPs in the GIPR gene have been associated with alterations in hormone and adipokine secretion in obese type 2 diabetic patients." (PMID 38903536, 2024). "Hence, the aim of the present study was to investigate the association of the rs34125392, rs4380143 and rs1800437 polymorphisms in the promoter, 5ʹ UTR and coding region of GIPR gene with type 2 diabetes mellitus in an Iranian population." (PMID 36882778, 2023). "Taking the changes in beta-cell mass of GIPRdn transgenic mice and pigs into account, screening for GIPR mutations in human subjects other than type 2 diabetics may be indicated." (PMID 21818396, 2011). "These peptides exhibited good therapeutic utility in type 2 diabetic animal models and, together with Amylin Pharmaceuticals, some of these long-acting GIPR agonists entered the therapeutic pipeline in 2006." (PMID 40024571, 2025). "This indicates the potential of changes in triacylglycerol composition to impact GLP-1R and GIPR activities, thereby increasing the onset of type 2 diabetes directly or indirectly within this patient group." (PMID 38614123, 2024). "GLP-1R, glucagon receptor (GCGR) and glucose-dependent insulinotropic polypeptide receptor (GIPR) are validated therapeutic targets for type 2 diabetes and obesity." (PMID 38346960, 2024). "However, little information is available regarding GIPR polymorphisms and type 2 diabetes mellitus (T2DM)." (PMID 36882778, 2023). "This SNP is an intronic variant in the gastric inhibitory polypeptide receptor (GIPR) gene and has previously been identified as associated with several lipid ratio traits and type 2 diabetes at the genome-wide level." (PMID 37579195, 2023). "Variation in GIPR is known to lead to impaired glucose tolerance and type 2 diabetes through an impaired incretin (a gut-derived peptide hormone) effect." (PMID 35771237, 2022). "Activation of the GLP-1R lowers blood glucose in persons with type 2 diabetes while the GIPR is much less effective for this." (PMID 36050763, 2022). "Co-localisation analysis showed evidence of a shared causal variant for type 2 diabetes liability and eight outcomes at the GIP gene, and six outcomes at the GIPR gene (PP > 0.8)." (PMID 34505161, 2021). "Evidence of co-localisation with genetic associations of type 2 diabetes liability at both the GIP and GIPR genes was observed for five outcomes." (PMID 34505161, 2021). "Coupled with reduced sensitivity in type 2 diabetic patients, development of GIPR-based therapeutics met little success." (PMID 34254582, 2021). "Glucagon-like peptide-1 (GLP-1) and glucose-dependent insulinotropic polypeptide (GIP) are important regulators of metabolism, making their receptors (GLP-1R and GIPR) attractive targets in the treatment of type 2 diabetes mellitus (T2DM)." (PMID 31330984, 2019). "The role in glucose regulation through insulin secretion suggests a therapeutic potential for GIPr agonism in type 2 diabetes." (PMID 23689510, 2013). "SNPs from GIPR, TCF7L2, CRY2, GLIS3 and SLC30A8 were also associated with type 2 diabetes (p = 0.0487∼2.0×10−8)." (PMID 21103350, 2010). "Agents incorporating GIPR agonism might optimally benefit patients with type 2 diabetes through improvements in both glucose tolerance and insulin sensitivity." (PMID 41287212, 2026).
type 2 diabetes (continued). "However, GIP receptor (GIPR) activity is diminished in patients with type 2 diabetes (T2D), while GLP-1 receptor (GLP-1R) function remains intact." (PMID 39963285, 2025). "Though clinical trial data support the efficacy of dual GIPR/GLP1R agonism for glycemic control in type 2 diabetes, it is unclear whether pharmacological GIPR agonism alone would confer similar favorable effects on glucose metabolism." (PMID 37250804, 2023). "The GIPR agonist tirzepatide was recently approved for the treatment of type 2 diabetes in adults." (PMID 37433298, 2023). "GIPR is a potential target for the treatment of type 2 diabetes mellitus." (PMID 35712239, 2022). "We examined whether genetic associations for type 2 diabetes liability in the GIP and GIPR genes co-localised with genetic associations for 11 cardiometabolic outcomes." (PMID 34505161, 2021). "After correction for multiple testing, type 2 diabetes–associated SNPs in or near HHEX, CDKAL1, IGF2B2, fasting glucose–associated SNPs in or near CDKAL1 and IGF2BP2, and a 2-hour glucose post-OGTT–associated SNP at the GIPR locus were all associated with beta-cell glucose sensitivity." (PMID 32944759, 2021). "It will be important to determine if post-translational modifications such as N-glycosylation are impaired in Type II diabetes, and whether this results in a reduction in cell surface GIPR and GLP-1R number along with the decreased incretin response of the ß-cell." (PMID 22412906, 2012). "Tirzepatide (LY3298176) is the first peptide dual agonist for type 2 diabetes mellitus (T2DM), which targets both GIPR and GLP1R." (PMID 38987789, 2024). "In clinical trials, treatment with tirzepatide produced superior weight loss and glycemic control compared to GLP-1RAs3,17, suggesting that agonism at both the GIPR and GLP-1R is beneficial in humans with type 2 diabetes." (PMID 37277609, 2023). "Tirzepatide is an agonist at both the GIPR and GLP-1R and is a highly effective treatment for type 2 diabetes and obesity." (PMID 37277609, 2023). "The receptors for the glucagon-like peptide-1 (GLP-1R), glucose-dependent insulinotropic polypeptide (GIPR), and glucagon (GCGR) are major pharmacological targets in metabolic diseases such as type 2 diabetes (T2D) and obesity." (PMID 33268378, 2021). "We showed SNPs from seven loci, including GIPR, TCF7L2, MADD, CRY2, GLIS3, PROX1 and SLC30A8, had an effect on type 2 diabetes in our samples." (PMID 21103350, 2010). "Both GLP-1 receptor agonists and DPP-IV inhibitors improve β-cell function and glycemic control in patients with type 2 diabetes, but there is controversy regarding the anti-diabetic potential for GIP receptor (GIPR) agonists." (PMID 20231880, 2010). "The most promising drug with GLP-1R/GIPR dual agonist effects is Tripeptide (LY3298176), developed by Eli Lilly and Company, which the Food and Drug Administration (FDA) has approved for treating type II diabetes and obesity." (PMID 39030216, 2024). "In a phase 3 clinical trial, tirzepatide, a dual GIPR/GLP1R agonist, was shown to confer superior HbA1c control as compared to GLP1R agonism alone and has recently been approved by the U.S. Food and Drug Administration (FDA) for type 2 diabetes treatment." (PMID 37250804, 2023). "If GIPR agonism induced by tirzepatide treatment is responsible for enhanced ß-cell secretion, it is reasonable to assume a time-dependent process re-establishing GIP as an effective insulin secretagogue even in advanced type 2 diabetes." (PMID 36050763, 2022). "Contrary to GLP-1RAs, selective GIPR agonists (GIPRAs) are not available for the treatment of type 2 diabetes." (PMID 31443356, 2019). "A number of key studies have suggested that GIP might promote weight gain: global germline GIPR knockout mice on a HFD display reduced body weight and maintain insulin sensitivity, whilst in patients with type 2 diabetes (T2D), the insulinotropic effect of GIP is impaired." (PMID 38653401, 2024).
type 2 diabetes (continued). "Combined glucose-dependent insulinotropic polypeptide receptor (GIPR) and glucagon-like peptide-1 receptor (GLP1R) agonism is superior to single GLP1R agonism with respect to glycemic control and weight loss in obese patients with or without type 2 diabetes." (PMID 37379656, 2023). "They interact with their cognate receptors (GIPR and GLP-1R), which are both members of the class B G protein-coupled receptors (GPCRs) and are already recognized as targets for the treatment of metabolic diseases, such as type 2 diabetes mellitus (T2DM) and obesity." (PMID 35953935, 2022). "Similarly, previous interaction findings for type 2 diabetes susceptibility genes, such as TCF7L2, GIPR, CAV2, and HFE, with other dietary factors were not replicated in the EPIC-InterACT study." (PMID 32722593, 2020). "Similar results were obtained when using variant–exposure associations for HbA1c levels rather than for type 2 diabetes liability (Pearson correlation of the MR β estimates = 0.99), and when using missense variant rs2291725 in GIP or eQTL variant rs12709891 in GIPR." (PMID 34505161, 2021). "Therefore, GIP receptor (GIPR) agonism has not been pursued in the treatment of type 2 diabetes, but novel GLP-1/GIP receptor agonists may soon redefine the pharmacological role of GIP." (PMID 31443356, 2019). "Regulation of GIPR and GLP-1R by N-glycosylation may have important implications for type 2 diabetes (T2DM)." (PMID 22412906, 2012).
diabetes (57 papers, 2010 to 2026). "Tirzepatide is a glucagon-like peptide-1 receptor (GLP-1R) agonist and glucose-dependent insulinotropic polypeptide receptor (GIPR) agonist that is used for diabetes mellitus and weight loss." (PMID 42226819, 2026). "The current focus areas for research are preventative factors to combat accelerated β-cell deterioration - a critical cause of diabetes - and exploring the benefits of GIPR." (PMID 35949358, 2022). "The gastric inhibitory polypeptide receptor (GIPR) can stimulate insulin release in the presence of elevated glucose; variants of GIPR were found linked with diabetes-related primary OAG." (PMID 33874942, 2021). "While the exact mechanisms behind the loss of GIP's insulinotropic action in diabetes remains obscure, several lines of experimental evidence suggest that GIPR is substantially down-regulated in pancreatic β-cells under a persistent hyperglycemic condition." (PMID 22536426, 2012). "We can thus infer that the down-regulation of GIPR in macrophages requires a long time, or that the suppression of GIPR expression is association with other metabolic alterations induced by diabetes." (PMID 22536426, 2012). "This may indicate diabetes-associated upregulation of GIPR in the jejunal muscle in response to reduced tissue GIP levels, as demonstrated in the present study." (PMID 41561152, 2025). "For example, the inclusion of GIPR targets in GLP-1R/GCGR agonists may buffer the risk of diabetes from chronic GCG receptor excitation." (PMID 40004115, 2025). "GIPR expression levels in response to diabetes, impaired glucose homeostasis or metabolic derangements are not known in humans." (PMID 40024571, 2025). "Here we report that tirzepatide (TZP), a novel polypeptide/glucagon‐like peptide 1 receptor (GIPR/GLP‐1R) agonist for the treatment of diabetes, has a role in attenuating CRC growth." (PMID 40125821, 2025). "Dietary habits influence the association of six genes (C2CD4B, CDKN2B, GIPR, HHEX, SLC2A2, and SLC30A8) forming the third cluster with diabetes, adipogenesis, and cardiovascular risk." (PMID 36982283, 2023). "A genetic risk score based on the diabetes risk alleles TCF7L2 rs7903146, KCNQ1 rs163184, KCNQ1 rs2237892, GIPR rs10423928 and WFS1 rs10010131 also showed a nominally significant interaction with coffee intake (p = 0.005)." (PMID 27623947, 2016). "The combined contribution of GIPR promoter methylation and diabetes status, age, sex and BMI to the variability in HOMA-IR was up to 23% and up to 53% regarding fasting glucose." (PMID 24086540, 2013). "The insulinotropic action of GIP virtually disappears in diabetes because of the severe down-regulation of GIPR in the pancreatic islets." (PMID 23967137, 2013). "· Hyperglycemia has been found to lower the expression of both GLP-1R and GIPR, contributing to the diminished incretin action in hyperglycaemic states and diabetes." (PMID 23110768, 2012). "The in vitro suppressive effect of GIP on foam cell formation was blunted in macrophages from diabetic mice vs. nondiabetic mice (15% vs. 35%), probably because of the reduced GIPR in the macrophages in diabetes." (PMID 22536426, 2012). "Likewise, the oligomerization of the glucagon-like peptide-1 receptor (GLP-1R) with the glucose-dependent insulinotropic polypeptide receptor (GIPR) in regulating post-endocytic insulin secretion offers a promising new approach for diabetes treatment." (PMID 40362321, 2025). "Genetic engineering of pigs represents an approach for diabetes mellitus research, including transgenic pigs expressing a dominant-negative glucose-dependent insulinotropic polypeptide receptor (GIPR) and ubiquitous expression of a dominant-negative human hepatocyte nuclear factor 1α (HNF1A)." (PMID 30823474, 2019). "· Activation of both GLP-1R and GIPR is known to stimulate insulin synthesis and insulin release, and both receptors have therefore been suggested as potential targets for the treatment of diabetes." (PMID 23110768, 2012).
diabetes (continued). "The study did report a positive association of the GIPR SNP with HDL but no results was provided for association analysis of biochemical parameters in diabetes and SNPs in GIP." (PMID 20673334, 2010). "Although TZP, as the first GLP‐1R/GIPR dual agonist, has been approved by the FDA for the treatment of diabetes, its anti‐tumor mechanisms and the specific relationship with receptors activation to downstream molecules still require further exploration." (PMID 40125821, 2025). "Despite the importance of the incretin-mimetics for diabetes therapy, our understanding of GLP1R and GIPR expression patterns and signaling within the islet remain incomplete." (PMID 38360354, 2024). "In summary, the collective evidence from various studies, including those exploring dual agonists (GLP-1R/GIPR) and tri-agonists (GLP-1R/GIPR/GCGR), demonstrates unprecedented improvements in diabetes and body weight compared to GLP-1RA treatment alone." (PMID 39145614, 2024). "From a multi-target perspective, the elevation in cAMP levels may not solely result from GLP-1R activation but could also involve other diabetes-related therapeutic targets such as DPP4, GIPR, and GCGR." (PMID 41373699, 2025). "The GIPR SNP rs10423928 was associated with the 2-h glucose level and the AUC ratio of insulin and glucose after an OGTT in participants without diabetes." (PMID 37049537, 2023). "Furthermore, several genes involved in the endocrine specification and diabetes development were significantly downregulated, such as HES1, INSM1, HNF1A, NEUROD1, NGN3, NKX2.2, GIPR, MNX1, PROX1, TCF7L2, and HHEX." (PMID 33473118, 2021). "Importantly, GLP-1 is not the only incretin involved in the pathogenesis of bone fragility in diabetes, with single GIP receptor (GIPR) KO and dual GLP-1R/GIPR KO mice presenting with enhanced bone fragility." (PMID 34093449, 2021). "In summary, CDKAL1 and GIPR-QPCTL loci showed the strongest associations with beta-cell glucose sensitivity by genome-wide and candidate gene-based approaches, and these associations were independent of diabetes status." (PMID 32944759, 2021). "In contrast to the case of GLP-1, no GIP receptor (GIPR) agonist is clinically utilized to date because its therapeutic potential was doubted by the observations showing impaired insulinotropic effects of GIP in individuals with diabetes." (PMID 32098413, 2020). "Therefore, it is possible that the relative activity of tirzepatide at the GLP-1R and GIPR may vary in subjects with and without diabetes as well as with the degree of hyperglycemia." (PMID 37277609, 2023). "In our study, we hypothesized that off-target interactions of specificdrugs with gut hormone receptors GLP1R, GIPR and GCGR could be a way to compensate for the negative influence of each on glucose homeostasis leading to drug-induced diabetes." (PMID 30682072, 2019).